RSC1A1 (regulator of solute carriers 1 )
Synonyms: RS1
Tractability: Antibody: UniProt places it where antibodies can reach, with high confidence; its Gene Ontology location is reachable by antibodies, with medium confidence. PROTAC: ubiquitination databases record sites on it.
Gene: Protein-coding gene on chromosome 1 (15,659,713 to 15,662,033, forward strand). Ensembl gene ENSG00000215695.
Pathways (Reactome):
Digestion and absorption: Intestinal hexose absorption
Transport of small molecules: SLC-mediated transport of organic cations
Gene Ontology:
Molecular function: protein binding; sodium channel inhibitor activity
Biological process: negative regulation of D-glucose transmembrane transport; negative regulation of Golgi to plasma membrane protein transport; negative regulation of nucleoside transport; negative regulation of transport; negative regulation of protein localization to plasma membrane
Cellular component: Golgi apparatus; nuclear body; nucleoplasm; plasma membrane; nucleus
Genetic constraint (gnomAD): Loss-of-function variants: 7 observed, 9.03 expected, observed/expected ratio (o/e) 0.78, 90% interval 0.44 to 1.45. That is too few expected variants to judge how well the gene tolerates losing a copy. Missense variants: 729 observed, 766.52 expected, observed/expected ratio (o/e) 0.95, 90% interval 0.89 to 1.01. Synonymous variants: 250 observed, 278.91 expected, observed/expected ratio (o/e) 0.9, 90% interval 0.81 to 1.
Homologues: Orthologues: macaque RSC1A1 (93% identical), pig RSC1A1 (73% identical), dog DDI2 (71% identical), guinea pig RSC1A1 (68% identical), mouse Ddi2 (54% identical), rat Ddi2 (53% identical).
Diseases named in the same sentence as RSC1A1 in open-access papers:
RSC1A1 is named in the same sentence as 1 disease in open-access papers, as found by Europe PMC text mining. Sharing a sentence is not in itself a finding about the gene and the disease.
RSC1A1 shares sentences with these, for which no sentence is quoted: breast carcinoma (1 paper).